LGR5 (leucine rich repeat containing G protein-coupled receptor 5)
Diseases named in the same sentence as LGR5 in open-access papers (continued):
Sharing a sentence is not in itself a finding about the gene and the disease.
tumor (continued). "The different tumor types also had different effects on CD26 expression: CD26 expression was unchanged when LGR5+ cells were targeted, was upregulated on targeting of LGR6+ cells, and was downregulated by targeting LRIG1+ cells." (PMID 26771241, 2016). "As an example, elevated levels of Lgr5 expression can be detected in CRCs and tumor cells with the highest level of Lgr5 have been shown to behave as functional CSCs both in humans and mice." (PMID 27355964, 2016). "We found that Lgr5+/CXCR4+ cells had significantly higher rates of tumor development, compared to others, based on bioluminescence examination." (PMID 27835894, 2016). "These insights establish that both R-spondins and Lgr5 can also display tumor suppressive features dependent on the context." (PMID 27355964, 2016). "Giving the injections at the beginning of the experiments enabled us to study clonal expansion of the Lgr5 progeny into the tumor." (PMID 27409834, 2016). "The tumour sphere formation assay indicated that ZG16 overexpression also significantly inhibited the sphere forming ability of LGR5+ CRC cells." (PMID 27880730, 2016). "HAPLN1 and the tumor progenitor cell markers CD44 and LGR5 were detected in tumor cells at the tumor-stroma interface and in cells arranged in an “Indian file” pattern." (PMID 27191501, 2016). "To further investigate the function of miR-196a in CRC tumor initiation, we firstly examined the expression of miR-196a in the isolated LGR5+ and LGR5- CRC cells." (PMID 27880730, 2016). "To further confirm the correlation between IKKα and LGR5, we analyzed LGR5 expression in skin BCC and metastasis biopsies using IHC." (PMID 27049829, 2016). "Throughout the tumorigenic period, the tumours that generated from pLenti-ZG16 stably transfected LGR5+ CRC cells grew significantly slower than those generated from pLenti-control transfected LGR5+ CRC cells." (PMID 27880730, 2016). "Meanwhile, the tumours that generated from p-miR-196a stably transfected LGR5- CRC cells grew significantly faster than those from p-miR-control transfected LGR5- CRC cells." (PMID 27880730, 2016). "We found that these Lgr5+/CXCR4+ cells showed higher tumor formation potential in vitro and in vivo, were more resistant to chemotherapy, and had a greater tumor-generating ability after serial adoptive transplantation." (PMID 27835894, 2016). "Immunohistochemical analysis showed that cytoplasmic LGR5 staining was observed in 9/25 poorly differentiated tumours (36%) and only 1/7 differentiating NBs (14%)." (PMID 26517508, 2015). "Many studies have demonstrated that Lgr5 protein is overexpressed in CRC and is associated with tumor initiation, 5-FU-based chemotherapy resistance, and recurrence." (PMID 26674601, 2015). "In the validation cohort, RSPO2 positivity strongly correlated with LGR5 tumor expression (p < 0.0001), with 80% of LGR5-positive tumors also staining positive for ligand RSPO2." (PMID 26416247, 2015). "LGR5 knockdown in all three of our tested cell lines led to a dramatic reduction in phosphorylated MEK/ERK which is a critical mediator of tumour cell survival and repressor of apoptosis." (PMID 26517508, 2015). "In an in vivo model of intestinal adenoma where adenomatous polyposis coli (APC) is deleted in LGR5+ intestinal stem cells, TIGAR deficiency decreases tumour burden and average tumour size, which results in increased disease-free survival in these mice." (PMID 25243985, 2015). "In contrast to moderate tumor volume changes, we observed a robust reduction in proportion of LGR5+ (3-fold) as well as CXCR4+ cells in OSI-906 treated xenografts compared to vehicle treated controls." (PMID 25895029, 2015). "The analysis of single cells isolated from human CRC tissue also showed that a subset of cells within the tumor expressed a gene signature similar to the Lgr5+ stem cell signature." (PMID 26399194, 2015).
tumor (continued). "In several of these cancers, high LGR5 expression is associated with the initiation, invasion, and metastasis of tumors, suggesting a potential role for LGR5 in tumor genesis." (PMID 26416247, 2015). "LGR5-siRNA cells formed smaller and fewer secondary tumor spheres than the NC and blank control cells." (PMID 24789370, 2014). "The correlation between LGR5 expression and the proliferative index (PI) of tumor cells by Ki-67 staining was evaluated." (PMID 24172981, 2014). "Our result is consistent with a previous report which showed that LGR5-overexpressing HaCaT cells resulted in tumor formation when transplanted into nude mice." (PMID 24172981, 2014). "First, we observed that LGR5 knockdown significantly inhibited the proliferation and secondary tumor sphere formation of HT29 spheroid cells in vitro." (PMID 24789370, 2014). "In contrast, many more Ki67 positive cells were found in the tumor tissues formed by the LGR5-overexpressing HeLa and SiHa cells than in those formed by the GFP HeLa and SiHa cells." (PMID 25193857, 2014). "High cytolasmic expression of the common marker of colon stem cells and CICs, Lgr5, was evident in some tumor parts, whereas in other parts, it was either moderately or weakly expressed (K), or even absent." (PMID 24921652, 2014). "In an intestinal adenoma model where APC is deleted in LGR5+ intestinal stem cells, mice deficient in TIGAR showed a reduction in total tumor burden and average tumor size in the small intestine compared to wild-type mice." (PMID 24383451, 2014). "In order to investigate the effect of LGR5 on survival of CCSCs, proliferation, tumor sphere formation, cell cycle and apoptosis assays were performed in LGR5-siRNA transfected HT29 spheroid cells." (PMID 24789370, 2014). "The weights of the tumor due to the LGR5-overexpressing cells (0.80±0.05 g) were also much heavier than those due to the HeLa-GFP control cells (0.35±0.03 g) (p<0.01)." (PMID 25193857, 2014). "Tumor xenograft experiments in nude mice indicated that LGR5 significantly promoted tumor growth in vivo." (PMID 25193857, 2014). "Genetic transformation of these Lgr5+ intestinal stem cells (ISCs) has shown their potential as tumor-initiating cells." (PMID 24926316, 2014). "The result showed that the average tumor weight of the LGR5-siRNA group was significantly lower than that of the NC group." (PMID 24789370, 2014). "Through knocking down or overexpressing LGR5 in SiHa and HeLa cells, the expression level of LGR5 was found to be positively related to cell proliferation in vitro and to tumor formation in vivo." (PMID 25193857, 2014). "Genetically engineered mice such as Lgr5-EGFP-IRES-creERT2/APCflox/flox mice allow the in situ observation of tumor generation from normal intestinal epithelium and the kinetics of the stem cells within the tumor." (PMID 24926316, 2014). "Our study demonstrated that the basal regions of tumor glands, which have a majority of the Lgr5+ cells, express significantly higher levels of ISC markers and CD133 than the upper region." (PMID 24340024, 2013). "In particular, we found that levels of LGR5 were highest in putative ES cancer stem cells as well as primary tumor biopsies obtained from patients with rapidly progressive and drug-resistant disease." (PMID 23596566, 2013). "The expression of OLFM4, EPHB2, and ASCL2 was relatively restricted to the basal region of tumor glands in the GA with basal LGR5 expression, but the expression of these markers was diffuse in the GA with a diffuse LGR5 expression pattern." (PMID 24340024, 2013). "To address this we analyzed the expression of LGR5 in a cohort of 49 primary ES tumor samples and 15 ES cell lines." (PMID 23596566, 2013). "LGR5+ cells were present in human GAs, where they accounted for 0 to >90% of the tumor cells with 2 main distribution patterns." (PMID 24340024, 2013).
tumor (continued). "The wide range and pattern of LGR5 expression in ES tumor samples and cell lines is consistent with patterns of LGR5 expression that have been discovered in other human cancers." (PMID 23596566, 2013). "The labeling index in the MDF (n=13) and in tumours (n=15) showed that the expression of LGR-5 was significantly increased (P<0.01) in both lesions compared with the surrounding normal mucosa." (PMID 23374535, 2013). "In both MDF (n=12) and tumours (n=15) cells co-expressing LGR-5 and nuclear β-catenin were observed (white arrow)." (PMID 23374535, 2013). "The Wnt-driven tumor initiation induced by targeted ablation of Apc tumor suppressor activity was also suspected to occur in the stomach LGR5+ cells." (PMID 24340024, 2013). "Given the concomitant Lgr5 upregulation in P3 cells, it is plausible that tumour-specific Paneth cells constitute the niche for Lgr5+ CSCs in Apc1638N/+/KRASV12G adenocarcinomas." (PMID 24069241, 2013). "The finding that LGR5 positivity declines with tumor progression and dedifferentiation suggests that Lgr5+ cells no longer act as tumor stem cells during the later stages of tumor progression." (PMID 24340024, 2013). "Lgr5 seems to be the first reported biomarker for stem cells in both normal intestinal mucosa and corresponding tumor tissues." (PMID 24340024, 2013). "Our observations emphasizes the necessity to consider the histoanatomic distribution of LGR5+ cells in tissue based studies, since the tumour biological effect is clearly related to their spatial distribution." (PMID 22530031, 2012). "Tumor tissues from esophagus, stomach, liver, pancreas, colon and rectum all show significantly more Lgr5 cells and higher levels of Lgr5-mRNA expression when compared with non-tumor tissues." (PMID 23217022, 2012). "In this study we tested the prevalence, histoanatomical distribution and tumour biological significance of the Wnt target protein and cancer stem cell marker LGR5 in tumours of the human gastrointestinal tract." (PMID 22530031, 2012). "The spatial histoanatomical distribution of LGR5+ cells has to be considered, when their tumour biological significance is explored in future studies." (PMID 22530031, 2012). "In the next step we grouped all patients together with LGR5+ tumour cells in the tumour centre and/or at the invasion front." (PMID 22530031, 2012). "With our experimental approach, we provide evidence that LGR5 is significantly up-regulated in a large variety of human hepato-gastrointestinal cancers relative to the tumour adjacent normal tissue." (PMID 22530031, 2012). "This showed a significant correlation between the presence of LGR5+ cancer cells in the tumour centre and the local tumour growth (T-category)." (PMID 22530031, 2012). "Distribution of Lgr5 cells in tumor center and invasion front of GC correlates well with tumor growth and nodal spread." (PMID 23217022, 2012). "The expression of LGR5 in the tumour centre and invasion front of GC correlated significantly with the local tumour growth (T-category) and the nodal spread (N-category)." (PMID 22530031, 2012). "This now showed that LGR5 expression correlated significantly with the local tumour growth (T-category), nodal spread (N-category) and tumour stage." (PMID 22530031, 2012). "Our results show that LGR5 is differentially expressed in gastrointestinal cancers and that the spatial histoanatomical distribution of LGR5+ cells has to be considered when their tumour biological significance is sought." (PMID 22530031, 2012). "In all tumour samples LGR5 staining was most prominent in the glands, particularly towards the gland lumen, and was weaker in the more amorphous areas of the tumour." (PMID 21829496, 2011). "We found that low expression of wild type LGR5/GPR49 mRNA (P = 0.023), as well as low expression of GPR49Δ5 mRNA (P = 0.005), was significantly associated with a higher tumor stage." (PMID 21978106, 2011).
tumor (continued). "The number of glands per field was increased in tumours overexpressing LGR5 (31+/−2, n = 16) however the difference from the parental tumours was not statistically significant." (PMID 21829496, 2011). "Bivariate analysis demonstrated that low expression of wild type LGR5/GPR49 mRNA correlated with higher tumor stage (P = 0.02)." (PMID 21978106, 2011). "LGR5 immunoreactivity was marginally elevated in tumours derived from LIM1899 cells transfected with pTune LGR5, but not in all areas of the tumours." (PMID 21829496, 2011). "Our results show that LGR5 silencing and overexpression have opposing effects on cell phenotype, including anchorage-independent growth, migration and tumour formation as xenografts in mice." (PMID 21829496, 2011). "Transfected and parental cells were expanded for two days, then harvested for parallel determination of LGR5 expression by qRT-PCR, clonogenicity ‘in vitro’ and tumour-forming capacity ‘in vivo’." (PMID 21829496, 2011). "Cells expressing siRNA to LGR5 showed enhanced tumour formation; conversely, cells overexpressing LGR5 were less tumourigenic." (PMID 21829496, 2011). "Several studies have already focused on the effects of different LgR5 expression in the context of tumor development and progression." (PMID 21345220, 2011). "These were Defcr4, S100A9, Igfbp5, Slc30a2 and Lgr5 (leucine-rich repeat containing G protein coupled receptor 5) which were up-regulated and Mptx, Slc26a3, Retnla, Muc2 and Hpgd (hydroxyprostaglandin dehydrogenase 15) which were down-regulated in tumours." (PMID 20459814, 2010). "With the increasing appreciation for the role of cancer stem cells or tumor-initiating cells in certain tumors, we sought to explore the expression of Lgr5 in normal and premalignant human gastrointestinal tissues." (PMID 19030762, 2008). "shRNA-mediated knockdown of β-catenin in CT26-shApc cells led to a reduction in the expression of β-catenin target genes, including Axin2 and Lgr5, and inhibited tumor cell proliferation in both WT Balb/c and immunodeficient nude mice without affecting CD8+ T cell infiltration." (PMID 41486293, 2026). "Leucine-rich repeat-containing G-protein coupled receptor 5 (LGR5), a member of the Wnt signaling pathway, is a transmembrane receptor that is highly expressed on certain cancer stem cells and plays an essential role in tumor cell proliferation and survival." (PMID 40565299, 2025). "Furthermore, markers of LGR5+ colon stem cells were suppressed in HG tumours, while markers of cell proliferation, fetal-like intestinal stem cells, and non-canonical cell types including mesenchymal cells were increased." (PMID 40473896, 2025). "Together these results indicate that LGR5 play either a suppressive or promoting role in tumor growth and effects may be cell-dependent." (PMID 39821694, 2025). "This analysis uncovered 2 tumor-associated epithelial populations, including a tumor-specific stem-like (tSTM, cluster 0) state defined by OLFM4 and LGR5, and a tumor-specific deep crypt secretory (tDCS, cluster 10) state characterized by REG4 with limited MUC2." (PMID 41282138, 2025). "LGR5+ cells are stem-cell-like and can initiate tumor growth and secondary tumors in distant sites." (PMID 39821694, 2025). "For instance, studies have shown that depleting LGR5+ CSCs may limit tumor growth, but tumors can still be maintained by LGR5 cells, which can revert to a CSC state when necessary." (PMID 40647402, 2025). "Petosemtamab may represent the first clinically effective therapy against the LGR5+ stem-cell-like cells within a tumor, frequently reported to be a central contributor to cancer growth, treatment resistance, and recurrence in CRC and other solid tumors." (PMID 40427162, 2025). "LGR5 + cells are responsible for self-renewal and differentiation into specialized cells, making them key players in both normal tissue regeneration and cancer, where they contribute to tumor growth and resistance to therapy." (PMID 39821694, 2025).
tumor (continued). "LGR5, a target gene of the Wnt signaling pathway, was commonly used to mark tumor stem cells." (PMID 40688093, 2025). "The strategy was effective in vitro and co-culture of human peripheral blood mononuclear cells (PBMC) and LGR5+ NALM6 (pre-B ALL) tumour cells in the presence of α-LGR5 bispecific led not only to robust CD4+ and CD8+ T-cell activation but also potent and specific tumour cell killing." (PMID 40405910, 2025). "A simple method leveraging the relative expression of LAPTM4B and LGR5 within tumor tissues may provide an accurate prediction of disease progression." (PMID 40661135, 2025). "Driving cells to differentiate away from LGR5+ tumor cells and form a population of LGR5++− tumor cells with immune evasion properties (LGR5++− represents the transition from immune-sensitive LGR5+ to immune-evading LGR5− states within the tumor cell population)." (PMID 41346579, 2025). "First, they used the KRAS inhibitor RMC‐9945 to force tumor cells into the Lgr5+ state." (PMID 41346572, 2025). "Through gene expression analyses of colon tissue, we identified significant increases in markers of tumor progression and microenvironment regulation, including LGR5, TWIST1, SNAIL, IL-8, CCL2, and COX2, in the colon of PSC patients compared with those with IBD alone." (PMID 40476597, 2025). "Furthermore, YTHDF1 expression was significantly elevated in CD133+/LGR5+ tumor cells relative to that in CD133-/LGR5- tumor cells." (PMID 41423446, 2025). "Herein, we also report that loss of markers of LGR5+ stem cells is associated with a compensatory enrichment of the fetal-like intestinal stem cell signature in HG CRC cell lines and primary tumours, identifying a further context in which this reprogramming occurs." (PMID 40473896, 2025). "LGR5 has been linked to angiogenesis through its role in promoting CSC, secreting angiogenic factors like VEGF, and interacting with the TME, all of which contribute to tumor vascularization and progression." (PMID 39821694, 2025). "In addition to the loss of markers of differentiated colonic epithelial cells, somewhat unexpectedly, HG CRC cell lines and primary tumours expressed lower levels of markers of LGR5+ colon stem cells." (PMID 40473896, 2025). "It is thus no surprise that LGR5 has attracted a great deal of therapeutic interest owing to its overexpression in cancers with de-regulated Wnt pathway activity relative to low levels in healthy tissues, and the fact that tumour cells require LGR5 for proliferation." (PMID 40405910, 2025). "Finally, we validated that VNP-siALKBH5 plus Oxaliplatin also markedly reduced tumor growth along with down-regulation of β-catenin, LGR5 and CD133 and induction of cell apoptosis in CSC28, indicating in vivo siALKBH5 enhances chemotherapy efficacy in CRC." (PMID 41390849, 2025). "In addition, the YTHDF1 and LGR5 proteins were consistently upregulated in CRC tumor tissues compared with paired adjacent normal tissues in the TCGA database." (PMID 41423446, 2025). "The majority of cancer studies have shown that LGR5 was associated with WNT/β-catenin signaling, which increases the expression of target genes like E-cadherin (cell adhesion marker) via EMT, enhancing tumor adhesion." (PMID 39821694, 2025). "Early preclinical ADC studies showed highly potent payloads could induce severe on-target, off-tumor toxicity in normal LGR5-expressing tissues despite anti-tumor efficacy, establishing that therapeutic index is critical." (PMID 41256852, 2025). "More recently, keywords such as mechanisms of LGR5 (+) stem cells, inflammation, intestinal homeostasis, tumor microenvironment, and gut microbiota have attracted increasing attention, suggesting they may evolve into dominant research trends in LGR5 studies." (PMID 41194856, 2025). "For example, anti-LGR5 antibodies may bind to LGR5 expressed on normal ISCs in addition to LGR5 expressed on the stem-cell-like cells within a tumor." (PMID 40427162, 2025).